ADAMTS15 (ADAM metallopeptidase with thrombospondin type 1 motif 15)
Diseases named in the same sentence as ADAMTS15 in open-access papers (continued):
Sharing a sentence is not in itself a finding about the gene and the disease.
tumor (19 papers, 2012 to 2025). "Further studies employing new strategies for qualitative and quantitative analysis of ADAMTS-15 expression are needed, particularly with a larger sample size and a broader range of tumor subtypes beyond mixed tumors." (PMID 39682243, 2024). "Immunohistochemical analysis of normal and cancerous tissues in CRC patients showed a decrease in ADAMTS15 expression in tumours compared to normal." (PMID 38948119, 2024). "ADAMTS15 encodes a member of the ADAMTS (a disintegrin and metalloproteinase with thrombospondin motifs) protein family and has been shown to function as a tumour suppressor by decreasing cell migration and invasion." (PMID 36305047, 2022). "ADAMTS-15 was also shown to be able to suppress tumor growth and migration, although it augmented survival." (PMID 33808504, 2021). "This suggests that the in vivo tumor suppressor function of ADAMTS-15 in these cells is significantly influenced by androgens." (PMID 32354091, 2020). "Collectively, these results are indicative of a tumor suppressor role for ADAMTS-15 that is dependent on its catalytic activity." (PMID 32354091, 2020). "This correlated with a significant decrease in tumor growth rate of those injected with ADAMTS-15 expressing LNCaP cells in comparison to those injected with pcDNA3.1 containing controls or ADAMTS-15EA expressing cells." (PMID 32354091, 2020). "For many family members, the dominant theme is tumor suppression as they show epigenetic silencing (ADAMTS1, 8, 9, 12 and 18) or mutational inactivation (ADAMTS15) in several cancer types." (PMID 26025392, 2015). "The same authors further went on to show that ADAMTS15 depleted cells showed enhanced in vivo tumor growth." (PMID 24213506, 2012). "Since similar inhibitory effects were also exhibited by a catalytically inactive form of ADAMTS15, the authors conclude that terminal TSRs are responsible for the anti-tumor function of ADAMTS15." (PMID 24213506, 2012). "The anti-tumor function of ADAMTS15 correlated with the ability of this protein to modulate Ras-dependent ERK pathway." (PMID 24213506, 2012). "Further work is required to determine the molecular basis behind ADAMTS15 tumour suppressive role in CRC, and whether this is dependent on its aggrecanase activity." (PMID 38948119, 2024). "Interestingly, in vitro studies showed reduced colony formation and cell invasion when wild-type ADAMTS15 was expressed in CRC cells compared to G489fs, suggesting that the mutation abrogates the tumour suppressive functions of ADAMTS15." (PMID 38948119, 2024). "ADAMTS15's role in tumor pathophysiology is inhibition of angiogenesis and cell migration." (PMID 38217262, 2024). "The clinical consequences of this mode of regulation are also difficult to predict, such that androgen deprivation therapy may serve to blunt the tumor suppressor functions of ADAMTS-15, the levels of which may separately become increased." (PMID 32354091, 2020). "ADAMTS-15 acts as a tumor suppressor in breast and colorectal cancer." (PMID 32354091, 2020). "Tumor-suppressive effects of the ADAMTSs have been linked to the deactivation of key proliferation or survival signaling pathways, including suppression of Erk signaling by ADAMTS8, ADAMTS12 and ADAMTS15, and of Akt/mTOR activity by ADAMTS9." (PMID 26025392, 2015). "Tumor cells expressing wild-type ADAMTS15 showed very low level of phospho-ERK." (PMID 24213506, 2012). "Additionally, an immunohistochemical analysis of normal versus tumor colorectal samples showed that ADAMTS15 expression was preferentially located to normal tissues." (PMID 24213506, 2012). "Moreover, androgens appeared to impact on the tumor suppressor role of ADAMTS-15." (PMID 32354091, 2020). "In the present study, the epithelial labeling of ADAMTS-15 was higher in CMT, a tumor with a better prognosis, compared to CSS, which has a worse prognosis." (PMID 39682243, 2024).
tumor (continued). "However, studies have suggested that the tumor-suppressive effects of ADAMTSs are linked to the deactivation of proliferation or invasion pathways, including inhibition of the ERK pathway by ADAMTS8, ADAMTS12, and ADAMTS15; and of the AKT/mTOR pathway by ADAMTS9." (PMID 27542224, 2016). "Loss of ADAMTS-15 in colorectal cell lines resulted in increased tumor growth both in vitro and in vivo, which could be reversed by the re-introduction of ADAMTS-15, although the level of expression did not correlate significantly with cancer grade." (PMID 32354091, 2020). "However, castrated mice injected with LNCaP cells expressing ADAMTS-15 no longer showed a significant difference to those injected with pcDNA3.1 controls or ADAMTS-15EA expressing cells in terms of survival or tumor growth." (PMID 32354091, 2020). "The median expression of ADAMTS-15 in stroma adjacent to in situ carcinomatous area was 120 in CSS and CMT, while in invasive areas, a median of 20 was obtained in this tumor type, despite there being no statistical difference (p = 0.7500)." (PMID 39682243, 2024). "In this setting mice injected with LNCaP cells expressing ADAMTS-15 showed no survival advantage when compared to those injected with cells expressing ADAMTS-15EA or pcDNA3.1 controls, with tumor growth rates no longer significantly different." (PMID 32354091, 2020).
cancer (7 papers, 2012 to 2024). A tumor composed of atypical neoplastic, often pleomorphic cells that invade other tissues. "Despite the fact that ADAMTS8 has been mainly reported to be downregulated in cancer, BC patients with low levels of ADAMTS15, in combination with high ADAMTS8 expression, showed the worst prolonged relapse-free survival." (PMID 38948119, 2024). "Members of the ADAMTS family, such as ADAMTS2, ADAMTS5, ADAMTS12, and ADAMTS15, can act as cancer suppressors or promoters." (PMID 33921267, 2021). "Members such as ADAMTS2, ADAMTS5, ADAMTS12, and ADAMTS15 act as cancer suppressors or promoters." (PMID 33921267, 2021). "Therefore, the fine balance between ADAMTS1 and ADAMTS15 could represent a mechanism to precisely tune the levels of syndecan-4 at the plasma membrane, to drive cancer cell migration." (PMID 38948119, 2024). "Thus, expression of ADAMTS15 may protect the organism from cancer development." (PMID 24213506, 2012). "In this study, ADAMTS-15 was more evident in stromal areas of CSS than in stromal areas of CMT, indicating that further studies are needed to understand the role of ADAMTS-15 and its localization in cancer." (PMID 39682243, 2024). "Finally, co-localization of ADAMTS-15, VCAN and versikine suggests ADAMTS-15 regulates VCAN cleavage as a likely mechanism to impact on cancer progression." (PMID 32354091, 2020).
ADAMTS15 also shares sentences with these, for which no sentence is quoted: gastric cancer (2 papers); chondrodysplasia (1); heart defects (1); Jacobsen syndrome (1); joint inflammation (1); lung carcinoma (1); osteoporosis (1); primary immunodeficiency (1); pulmonary fibrosis (1); pulmonary hypertension (1); schizophrenia (1); Thrombocytopenia (1).